HDAC1 (histone deacetylase 1)
Diseases named in the same sentence as HDAC1 in open-access papers (continued):
Sharing a sentence is not in itself a finding about the gene and the disease.
lupus (7 papers, 2010 to 2025). "Nineteen probes for 16 lupus-relevant genes (Abca1, Apobec3, Ccr7, Ceacam3, Ets1, Foxp3, Hdac1, Ifng, Irf9, Itgam, Jhdm1d, Mmp9, Oscar, Slc4a1, Tbx21, and Tlr7) were identified from the database of male murine spleen." (PMID 30246031, 2018). "Moreover, HDAC1 could promote CD4+T cell hyperactivation in systemic lupus erythematosus by repressing microRNA-124(miR-124) expression through promoter binding." (PMID 40895552, 2025). "In systemic lupus erythematosus (SLE), RFX1 downregulated IL17A, CD70, and CD11a expression by recruiting DNMT1, HDAC1, and SUV39H1 to alter epigenetic modifications in CD4+ T cells from patients with lupus." (PMID 30857550, 2019). "In addition, we found that the expression of HDAC1 and HDAC2 in the lupus tubulointerstitium tissue was significantly negatively correlated with the GFR of patients (R2 = 0.8172, p = 0.0052, and R2 = 0.8651, p = 0.0024 respectively)." (PMID 37153759, 2023). "In systemic lupus erythematosus (SLE), regulatory factor X 1 (RFX1) was found to be able to recruit HDAC1 to the promoter region of CD70 and deacetylate the histone substrate, resulting in a more condense chromatin structure and a decrease in the expression level of CD70." (PMID 35585975, 2022). "Besides the effects of HDACs on T cell activation, it has been reported that HDAC1 is recruited to the IgH enhancer region, and TSA treatment of B cells reduced the production of anti-DNA autoantibodies directly, highlighting the influence of HDACs on B cells in lupus mice." (PMID 30545086, 2018).
multiple sclerosis (7 papers, 2013 to 2023). A progressive autoimmune disorder affecting the central nervous system resulting in demyelination. "Remarkably, HDAC1 nuclear export has been already described in neurons under pathological stimuli and in multiple sclerosis brains and its export is linked to axonal damage and mitochondrial transport impairment." (PMID 37266450, 2023). "In the epigenetic modification under a diseased model of multiple sclerosis, serine phosphorylation of HDAC1 leads to its exporting to the cytosol." (PMID 34638996, 2021). "HDAC1 was reported to mediate the disruption of axonal transport and mitochondrial function in a multiple sclerosis mouse model." (PMID 34381129, 2021). "HDAC1, like most HDCAs, is a nuclear enzyme that can be re-localized in the cytosol in damaged axons of demyelinating models, such as in patients affected by multiple sclerosis and in cultured neurons exposed to glutamate or TNF-α52,53." (PMID 32409664, 2020). "The transportation to cytoplasm depends on the interaction between HDAC1 and nuclear Exportin 1 receptor (CRM1) and the cytosolic expression of HDAC1 is reported in damaged axons of multiple sclerosis patients, indicating that its export to the nucleus is necessary for its neurotoxic effect." (PMID 36358670, 2022).
Sepsis (7 papers, 2010 to 2026). Sepsis is defined as life-threatening organ dysfunction caused by a dysregulated host response to infection. "By elucidating the molecular mechanisms underlying HDAC1-mediated immunosuppression, we have provided potential strategies for developing immunomodulatory therapies for the treatment of sepsis." (PMID 41729078, 2026). "In this study, we investigated the role of histone deacetylase 1 (HDAC1) in sepsis-induced CD8+ T cell exhaustion, a key driver of immunosuppression." (PMID 41729078, 2026). "We further demonstrated that HDAC1 expression was significantly upregulated in CD8+ T cells from patients with sepsis." (PMID 41729078, 2026). "Our findings highlight HDAC1 as a potential therapeutic target for sepsis-induced immunosuppression." (PMID 41729078, 2026). "The levels of high-mobility group box chromosomal protein 1 (HMGB1), which are inhibited by increased levels of miR-124-5p and the downregulation of HDAC1, are dramatically increased in the myocardium in severe sepsis." (PMID 40660005, 2025). "HDAC1 levels are increased in the myocardial tissues of mice with sepsis, and these proteins bind to miR-124-5p, which leads to its downregulation." (PMID 40660005, 2025). "Third, investigations of histone deacetylases 1–3 (HDAC1–3), which are identified as deacetylases, will help reveal the role of H3K14la in sepsis‐induced EC activation." (PMID 39822760, 2025). "This process leads to the release of pro-inflammatory cytokines and worsens sepsis progression, whereas HDAC1 exerts the opposite effect." (PMID 39294473, 2024). "Inhibition of HDAC1 exacerbated the M1 macrophage polarization and pro-inflammatory cytokine production leading to the progression of LPS-induced sepsis, whereas CBP inhibition alleviated these symptoms." (PMID 39294473, 2024). "From our studies we find that epigenetic factors HDAC1, HDAC2 and DNMT3B show consistent differential expression compared to other sepsis cases, suggesting a role in disease susceptibility and pathogenesis." (PMID 28628607, 2017). "Overall, these findings indicated that CBP can promote TLR4-TIR acetylation, while HDAC1 may also serve as the deacetylase of TLR4-TIR in human CD16+ monocytes during sepsis." (PMID 39294473, 2024). "Although HDAC1 contributes to myocardial damage during sepsis, PI16 protects the heart by downregulating both HDAC1 and the Wnt3a/β-catenin pathway." (PMID 40660005, 2025). "Pharmacological inhibition of HDAC1, which deacetylates the TIR domains, or CBP play opposite roles in sepsis." (PMID 39294473, 2024). "Subsequently, we investigated the impact of CBP inhibitor and HDAC1 inhibitor on the progression of LPS-induced sepsis by intraperitoneally injecting TLR4-WT mice with SGC-CBP30, TSA, and HDAC1 inhibitor RG2833." (PMID 39294473, 2024). "For example, even though we showed that HDACs were upregulated in the HFD-fed mouse kidneys, expressions of HDAC1, 2, and 3 were fluctuated time-dependently but mostly reduced in lungs from mice with cecal ligation and puncture (CLP)-induced sepsis." (PMID 31655853, 2020). "DNMT3B, HDAC1 and HDAC2 were significantly up regulated in other sepsis cases compared to healthy controls." (PMID 28628607, 2017). "To determine if IRAK-M regulated the expression of Class 1 HDACs in sepsis, we isolated PM from WT and IRAK-M−/− mice at 0, 6, and 24 hrs post sham surgery or CLP and assessed for mRNA expression of HDAC-1, -2, -3, and -7." (PMID 20585389, 2010). "In addition, the expression of HDAC1 and HDAC3 was significantly reduced in CD16 + M1 macrophages from sepsis patients compared to that of normal individuals, particularly the HDAC1." (PMID 39294473, 2024). "Given the role of TLR4-TIR acetylation by CBP and HDAC1 in LPS-induced NF-κB activation, we conducted further investigations into the impact of CBP inhibitor and HDAC1 inhibitor on the polarization of M1 macrophages and the progression of sepsis." (PMID 39294473, 2024).
T-cell lymphomas (7 papers, 2014 to 2023). "We employed T cell lymphoma cell lines generated from a transgenic NPM-ALK mouse model harboring Hdac1 floxed alleles." (PMID 35954222, 2022). "Moreover, HDAC1/2 haploinsufficiency in mice causes a lethal pathology by T cell lymphomas with global histone acetylation and chromosomal instability, indicating an essential role for HDAC1/2 in the development of mature T cell populations and in maintaining genome stability." (PMID 31910827, 2020). "In a murine model, HDAC1 or 2 haploinsufficiency triggers T-cell lymphomas with global histone acetylation and chromosomal instability." (PMID 37533111, 2023). "In this study we elucidated the targets of HDACs in a murine T cell lymphoma model of ALCL by either pharmacological inhibition of HDACs or genetic deletion of Hdac1." (PMID 35954222, 2022). "Here we report that Cx3cr1-dependent combined ablation of Hdac1 and Hdac2 leads to delayed maturation of T-cell precursors and to development of T-cell lymphomas." (PMID 33849645, 2021). "Tissue array showed that HDAC1 was more frequently observed in T-cell lymphomas than in B-cell lymphomas (83.3% vs 38.9%, P = 0.016) and correlated with c-FLIP expression (r = 0.795)." (PMID 25477070, 2014). "Considering that HDAC1 was the main HDAC member involved in T-cell lymphomas, further study was focused on HDAC1 regulation by VPA and SAHA." (PMID 25477070, 2014). "Low levels of HDAC7 and HDAC1 or 2 activity are essential for T-cell lymphoma development." (PMID 37533111, 2023). "We isolated tumor cell lines from a transgenic mouse model of anaplastic large cell lymphoma (ALCL), a rare T-cell lymphoma, and abrogated HDAC activity by treatment with the HDACis Vorinostat and Entinostat or Cre-mediated deletion of Hdac1." (PMID 35954222, 2022). "Furthermore, we report that these mice develop a T-cell neoplasia at about 4–5 months of age, suggesting that a Cx3cr1 expressing subpopulation of immature T-cells gives rise to T-cell lymphomas in the combined absence of Hdac1 and Hdac2." (PMID 33849645, 2021).
B-cell lymphoma (6 papers, 2014 to 2023). "Here, we investigated the functional role of Hdac1 and Hdac2 using the Eμ-myc mouse model of B cell lymphoma." (PMID 27886239, 2016). "In this study, we used targeted conditional deletion of Hdac1 and Hdac2, to investigate the functional role of these enzymes in the Eμ-myc murine B cell lymphoma model." (PMID 27886239, 2016). "In view of these observations, we assessed the functional role of Hdac1 and Hdac2 in the development and progression of Eμ-myc driven B cell lymphomas." (PMID 27886239, 2016). "We further investigated the function of Hdac1 and Hdac2 in the Eμ-myc murine B cell lymphoma model." (PMID 27886239, 2016). "Our study raises the prospect of using selective HDAC1 and HDAC2 inhibitors for the treatment of BL and other B cell lymphomas with Myc deregulation, with possibly less side effects than pan-HDACis currently used." (PMID 27886239, 2016). "Instead, HDAC1 and DNMT1, the main known HDAC and DNMT factors in cancer have highest expression in hematopoietic malignancies, especially the B-cell lymphoma in the pan-cancer expression analysis (cBioportal) which may be the reason of the effectiveness of HDACi and DNMTi in treating these cancers." (PMID 28642588, 2017). "However, our data show that inhibition of STAT6 and c-myc expression by MPT0E028 may not be mediated by HDACs (HDAC1, 4, and 6) inhibition in B-cell lymphoma cell lines." (PMID 25669976, 2015).
colorectal adenocarcinoma (6 papers, 2013 to 2025). The most common type of colorectal carcinoma. "Our results also demonstrated HDAC1, 2 and 6 over-expressions in colorectal adenocarcinoma tissues." (PMID 26087180, 2015). "Selective knockdown of HDAC1, HDAC2, and a combination of both HDAC1 plus HDAC2 has been reported to increase the expressions of P-gp, MRP-1, and MRP2 in cell lines derived from human colorectal adenocarcinomas (HCT-8 and HCT-116)." (PMID 31191307, 2019). "In addition, a recent report shows that Histone Deacetylase 1 and 2 (HDAC1 and 2) have a reciprocal relationship to RB1 and are able to reduce ABCB1 and ABCC2 gene and protein expression in colorectal adenocarcinoma and carcinoma cell lines." (PMID 26799285, 2016). "Recently, resistance to the HDAC-inhibitor SAHA has been reported not to be accompanied by elevated expression of HDAC1 and HDAC3 in human colorectal adenocarcinoma cells." (PMID 23372654, 2013).
fibrosis (6 papers, 2014 to 2024). the formation of excess fibrous connective tissue in an organ or tissue in a reparative or reactive process. "Our results support the notion that increased renal HDAC1 and 2 expression and decreased histone acetylation are associated with high BP and acute renal injury with fibrosis." (PMID 39109516, 2024). "Global deletion of HDAC1 in mice results in early developmental arrest and embryonic lethality precluding the analysis of cardiac fibrosis in adult animals." (PMID 34869368, 2021). "Interestingly, inhibition of Class I HDACs with Mocetinostat reversed the cardiac fibrosis in CHF animals suggesting an association between cardiac fibrosis and HDAC1/2 upregulation." (PMID 25024745, 2014). "Interestingly, these downregulated miRNAs are also known to increase the expression of target genes HDAC1, HDAC2, and RB1 which increase global chromatin accessibility, increase cardiac fibrosis and decrease cardiac function." (PMID 33175850, 2020).
Infertility (6 papers, 2010 to 2023). "Bax and Cyclin A2 levels in MenSCs from healthy volunteers remain constant, HDAC1 levels increase, and in MenSCs from patients with infertility change: Bax levels decrease and Cyclin A2 levels increase." (PMID 34202508, 2021). "Inhibition of the HDAC1 expression can hinder spermatogenesis, reduce spermatogenesis, and lead to infertility." (PMID 33466297, 2021). "We report here a characterization of the infertility and sub-fertilty phenotypes observed in mice harboring Hdac1−/+/Hdac2−/− or Hdac2−/− oocytes, respectively." (PMID 23516383, 2013). "The infertility of mice harboring Hdac1−/+/Hdac2−/−oocytes is attributed to failure of those few eggs that properly mature to metaphase II to initiate DNA replication following fertilization." (PMID 23516383, 2013). "Further, deletion of both HDAC1 and HDAC2, however, results in infertility due to oocyte development arrest at the secondary follicle stage." (PMID 33842483, 2021). "The molecular basis for the sub-fertility of mice harboring Hdac2−/− oocytes or infertility of mice harboring Hdac1−/+/Hdac2−/−, however, was not examined." (PMID 23516383, 2013). "Furthermore, since DNMT1 and HDAC1 are two critical genes for proper epigenetic modification and development, changes to these genes may impact the results of maturation, fertilization, and embryonic development in PCOS mice, ultimately leading to infertility." (PMID 38102694, 2023).
ischemic stroke (6 papers, 2018 to 2025). A stroke disorder caused by obstruction of blood flow to the brain, due to thrombotic (local blood clot formation) or embolic (due to a blood clot or other material traveling from another site) event. "H19 can cause neuroinflammation by affecting histone deacetylase 1-dependent M1 microglial polarization and may be an important target for the therapy of ischemic stroke." (PMID 30778327, 2019). "This study identifies HDAC1 as a key epigenetic regulator that suppresses pro-inflammatory microglia activation and neuroinflammation following ischemic stroke." (PMID 41388741, 2025). "Taken together, these findings suggest that HDAC1 dysfunction drives microglia toward to a pro-inflammatory activation state, thereby contributing to heightened neuroinflammation following ischemic stroke." (PMID 41388741, 2025). "Previous studies have shown that HDAC1 expression increases after ischaemic stroke and that pharmacological inhibition promotes a shift of microglia from M1 to M2, exerting neuroprotective effects." (PMID 41388741, 2025). "This study demonstrates that HDAC1 is a pivotal epigenetic regulator of neuroinflammation after ischemic stroke, acting at the intersection of microglial activation, peripheral immune infiltration, and transcriptional reprogramming." (PMID 41388741, 2025). "This study aimed to investigate how HDAC1 dysfunction influences microglial activation states and contributes to neuroinflammatory processes in ischemic stroke." (PMID 41388741, 2025). "In contrast, our selective siRNA knockdown reveals that HDAC1 intrinsically represses NF-κB–driven pro-inflammatory activation, highlighting the importance of cellular context when defining its role in ischemic stroke." (PMID 41388741, 2025). "By targeting this pivotal early stage, our study provides mechanistic insight into how HDAC1 modulation influences microglial activation and the progression of neuroinflammation following ischemic stroke." (PMID 41388741, 2025). "Collectively, these findings demonstrate that selective reactivation of HDAC1 by Compound 5104434 mitigates microglial-driven neuroinflammation and promotes functional recovery following ischemic stroke." (PMID 41388741, 2025). "Its loss exacerbates inflammatory cascades, immune cell infiltration, and neuronal injury, underscoring HDAC1 as a potential therapeutic target for limiting secondary brain damage after ischaemic stroke." (PMID 41388741, 2025). "Understanding how HDAC1 dysfunction promotes neuroinflammation through pro-inflammatory microglial activation is critical for developing targeted therapeutic strategies for ischemic stroke." (PMID 41388741, 2025). "There are few reports on SAP30 in ischemic stroke, while HDAC1 has been reported to play a vital role in neurological diseases." (PMID 37386280, 2023). "In addition, the lncRNA H19 enhances neuroinflammation by driving HDAC1-dependent microglial M1 polarization during ischemic stroke." (PMID 34410604, 2021). "In ischemic stroke, the inhibition of both or either HDAC1 and HDAC2 reduce ischemic damage." (PMID 29362442, 2018). "Since HDAC1, 2, and 3 are strongly expressed in the central nervous system, a promising strategy may be to develop selective inhibitors of these enzymes in order to assess their effectiveness as a new therapeutic agent for ischemic stroke." (PMID 29362442, 2018).
nasopharyngeal carcinoma (6 papers, 2013 to 2025). A carcinoma arising from the nasopharyngeal epithelium. "Additionally, this Snail/HDAC1/HDAC2 complex is essential for EZH2-mediated repression of CDH1 in nasopharyngeal carcinoma cells." (PMID 40260239, 2025). "Moreover, upregulated EZH2 formed a co-repressor complex with HDAC1/HDAC2/Snail to inhibit E-cadherin which was responsible for the aggressiveness, invasion and metastasis of nasopharyngeal carcinoma cell." (PMID 24345883, 2013). "Similarly, it was reported that EVI1, which is overexpressed in Nasopharyngeal carcinoma, could bind to Snail and HDAC1 to suppress E-cadherin synthesis and thus enhance the EMT of nasopharyngeal cancer cells." (PMID 35897925, 2022).
cardiomyopathy (5 papers, 2017 to 2025). A disease of the heart muscle or myocardium proper. "The cardiomyopathy-associated targets were Dnmt1, Hdac1, Dot1l, Setd5, Nsd2, Usp3, Bap1, Prkca, Prkcb, Crebbp and Clock: 11 out of 81 (13.6% of total targets)." (PMID 40076868, 2025). "Double knockout HDAC1/2 in the heart leads to severe cardiomyopathy in mice, indicating the obligatory role for HDAC1/2 in specific tissues." (PMID 32848876, 2020).
cognitive decline (5 papers, 2018 to 2025). "Mice lacking HDAC1 experience age-related DNA damage accumulation and cognitive decline, as HDAC1 stimulates OGG1 activity to remove 8-oxoG lesions linked to transcriptional repression." (PMID 40940748, 2025). "Our results indicate that loss of HDAC1 results in age-dependent cognitive decline, paralleled by reduced OGG1 activity and 8-oxoG lesion accumulation." (PMID 32424276, 2020). "Assaying blood HDAC1 levels may thus be a useful method for screening patients at higher risk in cognitive decline." (PMID 30341976, 2018). "HDAC1 levels are notably reduced in AD patients, which correlates with increased amyloid-β and tau protein levels, brain atrophy, and cognitive decline." (PMID 40940748, 2025). "Despite the lack of gross brain abnormalities, Hdac1 cKO mice exhibited age-dependent cognitive decline." (PMID 32424276, 2020).
gastric tumors (5 papers, 2017 to 2022). "The gene expression of histone deacetylase 1 was observed to be higher in gastric tumors than in normal tissue, while the expression of the histone acetylase gene was observed to be lower in normal tissues than in gastric tumors." (PMID 36010915, 2022). "miR-520h could play a tumor suppressive role in gastric tumors by targeting HDAC1." (PMID 32775453, 2020).